PYCR2 (pyrroline-5-carboxylate reductase 2)
Description:
Oxidoreductase that catalyzes the last step in proline biosynthesis, which corresponds to the reduction of pyrroline-5-carboxylate to L-proline using NAD(P)H. At physiologic concentrations, has higher specific activity in the presence of NADH. Involved in cellular response to oxidative stress. In some cell types, such as erythrocytes, its primary function may be the generation of NADP(+).
Synonyms: P5CR2; HLD10
Tractability: PROTAC: ubiquitination databases record sites on it; its protein half-life has been measured.
Target class: Enzyme; Oxidoreductase
Gene: Protein-coding gene on chromosome 1 (225,919,397 to 225,924,340, reverse strand). Ensembl gene ENSG00000143811.
Subcellular location: Cytoplasm; Mitochondrion
Subcellular location (Human Protein Atlas): Mitochondria
Pathways (Reactome):
Metabolism: Glutamate and glutamine metabolism
Gene Ontology:
Molecular function: protein binding; pyrroline-5-carboxylate reductase activity
Biological process: cellular response to oxidative stress; L-proline biosynthetic process; L-glutamate catabolic process; L-glutamine catabolic process
Cellular component: cytoplasm; mitochondrion; cytosol; mitochondrial matrix
Genetic constraint (gnomAD): Loss-of-function variants: 19 observed, 27.1 expected, observed/expected ratio (o/e) 0.7, 90% interval 0.49 to 1.03. The upper end of that interval is the gene's LOEUF score, 1.03, which puts it in group 4 of 6, group 1 being the genes least tolerant of losing a copy. Missense variants: 380 observed, 423.34 expected, observed/expected ratio (o/e) 0.9, 90% interval 0.82 to 0.98. Synonymous variants: 172 observed, 175.89 expected, observed/expected ratio (o/e) 0.98, 90% interval 0.86 to 1.11.
Homologues: Orthologues: chimpanzee PYCR2 (99% identical), guinea pig PYCR2 (96% identical), pig PYCR2 (95% identical), rabbit PYCR2 (94% identical), rat Pycr2 (92% identical), mouse Pycr2 (92% identical), dog PYCR2 (83% identical), tropical clawed frog pycr1 (78% identical), zebrafish pycr1b (77% identical), zebrafish pycr1a (77% identical), Caenorhabditis elegans pycr-1 (42% identical), Drosophila melanogaster P5cr-2 (36% identical). Paralogues in human: PYCR1 (84% identical), PYCR3 (38% identical), NOXRED1 (18% identical).
Diseases named in the same sentence as PYCR2 in open-access papers:
PYCR2 is named in the same sentence as 38 diseases in open-access papers, as found by Europe PMC text mining. Sharing a sentence is not in itself a finding about the gene and the disease. The quoted sentences say what the papers report.
microcephaly (8 papers, 2015 to 2023). A congenital or acquired developmental disorder in which the circumference of the head is smaller than normal for the person's age and sex. "Since HLD10 displays progressive microcephaly and reduced cerebral white matter volume, HLD10-associated PYCR2 mutations appear to lead to developing abnormalities in the whole brain." (PMID 36548190, 2022). "This nonpolar amino acid has been linked to seizures and cognitive dysfunction, as well as to PYCR2 gene expression linked to microcephaly and hypomethylation, along with the PARS2 gene related to infantile-onset encephalopathy." (PMID 35629950, 2022). "In addition to these previously reported ClpXP-interacting proteins, pyrroline-5-carboxylate reductase 2 (PYCR2), the genetic mutation of which causes microcephaly, was also identified." (PMID 37660922, 2023). "Moreover, the homolog of PYCR1, PYCR2, induces mutations related to microcephaly and hypomyelination." (PMID 31428683, 2019). "In another genetic disorder that is characterized by microcephaly and hypomyelination (the absence of lax and wrinkled skin), a mutation has been identified at residue Arg119 in PYCR2 which corresponds to the same mutated region in PYCR1 in affected individuals." (PMID 28194412, 2017).
melanoma (6 papers, 2012 to 2024). A malignant, usually aggressive tumor composed of atypical, neoplastic melanocytes. "This aligns with research indicating PYCR1 in tumors such as colorectal cancer, bladder cancer, and gastric cancer, among others, and PYCR2 in colorectal cancer, hepatocellular carcinoma, melanoma, and other cancers." (PMID 39125668, 2024). "Knocking out PYCR2 inhibits the proliferation, migration, and invasion of colon cancer and also influences the development of melanoma, bladder cancer, nasopharyngeal carcinoma, gastric cancer, and other tumors." (PMID 39125668, 2024). "Confirming the high dependence of melanoma on proline metabolism, siRNA-mediated knockdown of PYCR2 was found to reduce proliferation and provoke a mild increase in apoptosis in melanoma cells." (PMID 33083024, 2020). "There is a study about skin cancer that identified that PYCR2 was abundantly present in melanoma cells and regulated the Akt/mTOR pathway." (PMID 31428683, 2019). "Three enzymes involved in the biosynthetic route from glutamate to proline (P5CS, PYCR1 and PYCR2) are up-regulated in melanoma compared to melanocytes." (PMID 23024808, 2012). "PYCR2 indispensable for the regulation of energy metabolism, and studies have reported that PYCR2 silence activates AMPK/mTOR pathway induced autophagy in melanoma can regulate downstream genes through the AMPK/mTOR pathway." (PMID 37325047, 2023). "Moreover, isotope enrichment experiments in melanoma cell lines showed that PYCR1 and PYCR2 primarily catalyze the synthesis of L-proline from glutamate, although, in the presence of high levels of ornithine, PYCR1 can also produce L-proline through ornithine." (PMID 33083024, 2020). "PYCR1 and PYCR2 are abundant in melanoma cells but not detected in melanocytes." (PMID 23024808, 2012). "Given the paucity of information on PYCR2 and PYCRL, and the lack of information on the role of each PYCR along the two biosynthetic routes to proline, we compared their cellular function and enzymatic properties in melanoma cells lines." (PMID 23024808, 2012).
glioma (5 papers, 2018 to 2024). A benign or malignant brain and spinal cord tumor that arises from glial cells (astrocytes, oligodendrocytes, ependymal cells). "To determine whether the same phenotype was observable in vivo, we first investigated the expression of PYCR1 and PYCR2 in low-grade gliomas, in which IDH1 mutations are commonly observed." (PMID 29562167, 2018). "TRA2A is highly expressed in breast cancer, glioma, and liver cancer, while PYCR2 is regarded as a prognostic biomarker in the HBV-related HCC." (PMID 35669517, 2022). "The Chinese Glioma Genome Atlas (CGGA) and The Human Protein Atlas (HPA) databases were utilized to investigate the relationship between ALKBH5 and PYCR2." (PMID 37325047, 2023). "Therefore, although our results indicate significant differences only in the PYCR1 isoform, it would seem appropriate to refrain from definite conclusions dismissing the role of PYCR2 and PYCR3 in gliomas until the wider context of the multi-layered metabolic network involved is better understood." (PMID 38275897, 2024).
breast carcinoma (4 papers, 2019 to 2025). "For example, c-Myc transcription regulates PYCR2, thereby activating the AKT signaling pathway to promote the invasion and metastasis of breast cancer." (PMID 41331125, 2025). "Western blot analysis of 17 breast cancer cell lines showed higher protein expression of GLS and TYMS in TNBC cell lines compared to ER+ and HER2-amplified cell lines, and higher expression ALDH18A and PYCR2 in TNBC compared with ER+ cell lines." (PMID 36388465, 2022).
hepatocellular carcinoma (4 papers, 2020 to 2024). A malignant tumor that arises from hepatocytes. "Conversely, PYCR2, while less studied, shows promise as a prognostic biomarker in hepatocellular carcinoma and colorectal cancer, with PYCR3 having limited exploration primarily in nasopharyngeal cancer." (PMID 39125668, 2024). "Although E4B is highly expressed, it hardly degrades TRA2A and PYCR2 in hepatocellular carcinoma (HCC) cells, suggesting other mechanisms exist for degradation of TRA2A and PYCR2 in the HCC cells." (PMID 35669517, 2022). "In Huh7.5 hepatoma cells, the expression of proteins synthesizing proline from P5C (PYCR1, PYCR2, PYCR3) prevails over proline-utilizing proteins (PRODH and PRODH2) and the coordinated action of PYCR3, PRODH, and PRODH2 proteins." (PMID 37189460, 2023). "The change of proline expression is the most significant factor in amino acid metabolism in hepatocellular carcinoma (HCC), and PYCR2 is abnormally expressed in the esophageal squamous cell carcinoma (ESCC), indicating that PYCR2 may play a key role in cancer progression." (PMID 35669517, 2022).
colorectal cancer (3 papers, 2021 to 2025). A primary or metastatic malignant neoplasm that affects the colon or rectum. "The aim of this study was to investigate the effect and underlying pathway of pyrroline-5-carboxylate reductase-2 (PYCR2) on colorectal cancer (CRC)." (PMID 34512817, 2021).
colon cancer (2 papers, 2023). "Overall, our data support findings from recent studies suggesting an association between PYCR2 and colon cancer aggressiveness." (PMID 37508547, 2023). "PYCR2 is a key enzyme of the proline biosynthetic pathway; thus, we examined whether the loss of PYCR2 was sufficient to decrease proline levels in colon cancer cells." (PMID 37508547, 2023). "However, our study builds on these initial findings and not only confirms the causal role of PYCR2 in promoting tumorigenicity and the invasive mobility of colon cancer cells in vitro but also in vivo oncogenic growth by regulating MASTL/Wnt/β-catenin signaling." (PMID 37508547, 2023). "Taken together, our data identify a novel PYCR2/MASTL/Wnt/β-catenin signaling pathway that promotes colon cancer." (PMID 37508547, 2023). "Overall, the outcome of the current study identifies PYCR2 as a novel biomarker of colon cancer progression and poor prognosis and a potential therapeutic target." (PMID 37508547, 2023). "The subcutaneous injection and intramucosal transplantation of control and PYCR2-inhibited colon cancer cells were utilized for the in vivo tumor growth studies." (PMID 37508547, 2023). "We thus further analyzed if the expression of colon cancer stem cell markers is also differentially expressed in PYCR2-manipulated CRC cells." (PMID 37508547, 2023). "Taken together, our data highlight the significance of PYCR2 as a novel therapeutic target for effectively treating aggressive colon cancer." (PMID 37508547, 2023). "We further demonstrated that MASTL overexpression promotes colon cancer aggressiveness by promoting cancer stem cells, similar to PYCR2." (PMID 37508547, 2023). "Moreover, our data showed that PYCR2 regulates p-Akt expression in CRC cells, supported by a recent study that found that PYCR2 activates PI3K/AKT signaling in colon cancer cells." (PMID 37508547, 2023). "PYCR2 is up-regulated in colon cancer and enhances cell proliferation, migration, and invasion." (PMID 37325047, 2023). "In this regard, we first examined PYCR2 expression in a panel of colon cancer cell lines." (PMID 37508547, 2023). "A similar outcome was reported by recent studies Our data from a protein expression analysis of the CPTAC database and an IHC analysis of CRC adenomas and adenocarcinomas supported a significant increase in PYCR2 levels in colon cancer but also demonstrated that it is an early event." (PMID 37508547, 2023). "Taken together, these data supported the role of PYCR2 in promoting colon cancer." (PMID 37508547, 2023). "Overall, in this current study, we establish the specific role of PYCR2, out of the other PYCR enzymes, as a critical regulator of cellular proline homeostasis in colon cancer." (PMID 37508547, 2023).
esophageal squamous cell carcinoma (2 papers, 2021 to 2022). Esophageal squamous cell carcinoma (ESCC) is a type of esophageal carcinoma (EC) that can affect any part of the esophagus, but is usually located in the upper or middle third. "This approach revealed, for example, that the functions of pyrroline-5-carboxylate reductase 2 (PYCR2) and uridine phosphorylase 1 (UPP1) are altered in esophageal squamous cell carcinoma." (PMID 33401771, 2021).
hypomyelinating leukodystrophy 10 (2 papers, 2022 to 2024). Any leukodystrophy in which the cause of the disease is a mutation in the PYCR2 gene. "Purine-Rich Element-Binding Protein A (PURA) causes a neurodevelopmental disorder with neonatal respiratory insufficiency, hypotonia, and feeding difficulties (MIM#616158), and Pyrroline-5-Carboxylate Reductase 2 (PYCR2) causes hypomyelinating leukodystrophy 10 (MIM#616420)." (PMID 37563452, 2024).
adenoma (1 paper, 2023). A neoplasm arising from the epithelium. "Therefore, to examine if PYCR2 expression in CRC is associated with a specific adenoma type, we utilized adenomas and adjacent normal colons from CRC patients to determine if increased PYCR2 expression is associated with a specific CRC type." (PMID 37508547, 2023).
cervical cancer (1 paper, 2022). A primary or metastatic malignant neoplasm involving the cervix. "A1AT, PYCR2, TTR, ApoAI, VDBP, and MMRN1 were expressed considerably differently in serum samples from healthy controls and cervical cancer patients." (PMID 35645371, 2022).
CLN7 disease (1 paper, 2021). "We identified other inherited metabolic disorders including pyridoxine-dependent epilepsy (PDE) due to biallelic variants in ALDH7A1, PYCR2 disease, EARS2 disease, PARS2 disease, CLN7 disease, and glucose transporter 1 deficiency syndrome with or without liver dysfunction in our study cohort." (PMID 34440401, 2021).
colon adenoma (1 paper, 2023). An adenoma that arises from the colon. "A similar trend was also observed in human colon adenomas (p < 0.0001) and adenocarcinomas (p < 0.0001), supporting the role of PYCR2 in CRC development." (PMID 37508547, 2023). "However, we found no major differences in PYCR2 expression between different histological subtypes of colon adenomas by quantifying the PYCR2 staining intensity score." (PMID 37508547, 2023).
glioblastoma (1 paper, 2023). The most malignant astrocytic tumor (WHO grade IV). "According to the WHO classification, ALKBH5 and PYCR2 were more highly expressed in grade IV glioblastoma." (PMID 37325047, 2023).
Intellectual disability (1 paper, 2025). "PYCR2 deficiency, in particular, leads to profound neurodevelopmental phenotypes, including microcephaly, brain atrophy, and severe intellectual disability." (PMID 41200384, 2025). "Mutations in PYCR2 are linked to HIDEA syndrome, a neurodevelopmental disorder featuring hypotonia, intellectual disability, epilepsy, and structural brain abnormalities." (PMID 41200384, 2025).
lymphoma (1 paper, 2021). A malignant (clonal) proliferation of B- lymphocytes or T- lymphocytes which involves the lymph nodes, bone marrow and/or extranodal sites. "Up-regulation of mitochondrial PYCR1 and PYCR2 is observed in a number of cancer types, such as prostate cancer and lymphoma." (PMID 34822010, 2021).
renal carcinoma (1 paper, 2024). A carcinoma arising from the epithelium of the renal parenchyma or the renal pelvis. "Varying proline concentrations showed similar effects, indicating that PYCR1 and PYCR2 activate mTOR via proline synthesis, influencing renal cancer cell proliferation and migration." (PMID 39125668, 2024). "The expression levels of PYCR1 and PYCR2 in renal cancer cells were significantly higher than those in normal kidney tissue, consistent with the results of the previous analysis." (PMID 39125668, 2024). "The biological functions and regulatory mechanisms of PYCR1 and PYCR2 were investigated by in vitro experiments in renal cancer cells." (PMID 39125668, 2024). "Overall, these results suggest that overexpressing PYCR1 and PYCR2 in vitro can promote the growth and migration of renal cancer cells." (PMID 39125668, 2024). "We validated the expression of PYCR1 and PYCR2 in normal human kidney tissue and renal cancer cell lines Caki-1, 786-O, and A498." (PMID 39125668, 2024). "In vitro experiments demonstrated that PYCR1 and PYCR2 enhanced the proliferation and migration of renal carcinoma cells by activating the mTOR pathway, at least in part." (PMID 39125668, 2024). "In conclusion, these results indicate that inhibiting PYCR1 and PYCR2 in vitro can suppress the growth and migration of renal cancer cells." (PMID 39125668, 2024). "Given the impact of PYCR1 and PYCR2 knockdown and overexpression on the biological functions of renal cancer cells, we further investigated the potential molecular mechanisms involved in KIRC." (PMID 39125668, 2024). "Considering PYCR1, PYCR2, and HF effects on the mTOR pathway, these findings suggest targeting proline metabolism, especially via HF-mediated inhibition, as a potential therapeutic approach for renal cancer." (PMID 39125668, 2024). "In our experiments, silencing PYCR1 and PYCR2 in renal cancer cell line Caki-1 and A498 cells resulted in inhibited cell growth and migration, whereas overexpression of PYCR1 and PYCR2 promoted cell growth and migration." (PMID 39125668, 2024). "Finally, we explored the impact of PYCR1 and PYCR2 on cell growth and migration in renal cancer cells, revealing that PYCR1 and PYCR2 may exert their effects on renal cancer by activating the mTOR signaling pathway." (PMID 39125668, 2024).
renal cell carcinoma (1 paper, 2024). "We investigated the biological effects of overexpressing PYCR1 and PYCR2 in the human renal cell carcinoma Caki-1 and human embryonic kidney 293T cells in vitro." (PMID 39125668, 2024). "We knocked down PYCR1 and PYCR2 in the human renal cell carcinoma cell lines Caki-1 and A498 cells to investigate their biological functions in KIRC cells." (PMID 39125668, 2024).
schizophrenia (1 paper, 2024). A major psychotic disorder characterized by abnormalities in the perception or expression of reality. "In contrast, the level of the proline synthesis enzyme PYCR1 was higher in schizophrenia patients, although two other proline synthesis enzymes, ALDH18A1 and PYCR2, exhibited slightly lower levels compared to healthy controls." (PMID 37815900, 2024).